IL1B (interleukin 1 beta)
Diseases named in the same sentence as IL1B in open-access papers (continued):
Sharing a sentence is not in itself a finding about the gene and the disease.
depression (continued). "Our previous studies have found that chronic unpredictable mild stress (CUMS) stimuli induced depression-like behaviors, increased levels of IL-1β and IL-18 and altered the microbiota, which suggested NLRP3 inflammasome might be activated." (PMID 37293210, 2023). "Interestingly, IL-1β and IL-18 are significantly increased in patients with MDD, and their levels are associated with the severity of depression." (PMID 37369673, 2023). "Furthermore, isorhamnetin and similar flavonols have been found to normalize proinflammatory cytokines such as TNF-α and IL-1β in both the periphery and the brain of experimental animals or plasma samples from patients diagnosed with depression." (PMID 37754268, 2023). "The increase in IL-1β that we observed in the two-exposure groups may indicate a transient depression/PTSD-like inflammatory state that is dampened following further blast exposures." (PMID 37628746, 2023). "We can cautiously claim that DIO1 and DIO3 and pivotal cytokines, mainly IL-1β and IL-6, may play a role in depression diagnosis, and further studies are suggested to explain the exact role of these molecules in larger samples with more precise methods." (PMID 37834806, 2023). "Relative gene expression changes in different inflammatory markers involved in allergic processes (TNFα, IL-1β, IL-4, IL-5, IL-6, and IL-13) were analyzed in the orbitofrontal cortex of suicide completers with a history of major depressive disorder (MDD) versus controls." (PMID 38069051, 2023). "In the pain-depression dyad model, we evaluated immobile time, neurotransmitter levels, interleukin-1 (IL-1β) and tumor necrosis factor-α (TNF-α) levels, and the expression of mRNA of brain-derived neurotrophic factor (BDNF) and tryptophan hydroxylase 2 (Tph2)." (PMID 38259687, 2023). "Interestingly, studies in an animal model of depression indicated that nuclear factor kappa B is a major mediator, linking stress-induced increases in IL-1β with compromised hippocampal neurogenesis and depressive behavior." (PMID 36978923, 2023). "Additionally, other pro-inflammatory cytokines showed similar outcomes in depression like IL-1β, TNF- α, and IL-18." (PMID 37957650, 2023). "An experimental animal study showed that the improvement of depression-like behavior by FMT may be associated with an increase in 5-HT levels and decreases in IL-1β and TNF-α levels." (PMID 38057705, 2023). "Therefore, TET2 affects the activation of NLRP3/IL-1β pathway in microglia, which plays an important role in the occurrence and development of AR anxiety and depression-like behavior." (PMID 38012545, 2023). "The development of depression is often accompanied by an increased inflammatory response, which increases levels of peripheral and central pro-inflammatory cytokines, including interleukin-1β (IL-1β), interleukin-6 (IL-6), and tumor necrosis factor-α (TNF-α)." (PMID 38094892, 2023). "And in terms of peripheral and central inflammation, some studies have suggested that ECT in patients with depression activates peripheral blood mononuclear cells in 30 min, increases circulating pro-inflammatory factors such as IL-1β and IL-6 at 3 h, and falls back to baseline at 24 h." (PMID 36624089, 2023). "In addition, the results revealed that compared with the control group, the levels of TNF‐α and IL‐1β were significantly increased in CUMS‐induced depression‐like mice." (PMID 37408379, 2023). "Because of the well-documented role of the P2X7R in IL-1β release, it is hypothesized that P2X7R antagonists may be beneficial for depression associated with neuroinflammation." (PMID 37482560, 2023). "The outcome measures were plasma IL-6 and IL-1β concentrations and a questionnaire including the Pittsburgh Sleep Quality Index, the Center for Epidemiology Research Depression Scale, the Somatic Symptoms Inventory, the Perceived Stress Scale, and the Holistic Body–Mind–Spirit Well-Being Scale." (PMID 37509542, 2023).
depression (continued). "Furthermore, the present study revealed that CORT-induced depression in mice resulted in notable depression symptoms, increased levels of pro-inflammatory factors, including IL-1β and TNF-α, and an increase in NF-κB phosphorylation." (PMID 37954847, 2023). "In this way, the level of IL-1β and the −511C/T genotype, alone or together, may be biomarkers of depressive disorder." (PMID 37510364, 2023). "Targeted interventions for people with higher levels of IL-1β and the IL1B-511T allele may reduce the risk of depressive disorder." (PMID 37510364, 2023). "Furthermore, the proinflammatory cytokines TNF-α, IL-1β, and IL-6 have been reported to be raised in rodents that exhibited a depression-like phenotype." (PMID 35939172, 2022). "Similarly, a previous systematic review and meta-analysis showed that the expression levels of IL-1β and IL-6 were significantly elevated in elderly patients with depression." (PMID 35496273, 2022). "However, in a systematic review and meta-analysis of studies examining plasma levels of IL-1β, IL-6, TNFα, and CRP in elderly patients with depression or Alzheimer’s disease, IL-1β was measured in eleven studies between 2005 and 2018." (PMID 35821823, 2022). "This suggests that NLRP3, caspase-1, and IL-1β may be involved in the anxiety-like and depression-like behavioral phenotypes of AD mice." (PMID 36267291, 2022). "Hence, serum TNF‐α, IL‐1β, IL‐6, and IL‐17 were positively related to anxiety and depression in NSCLC survivors." (PMID 34697903, 2022). "Furthermore, a large body of evidence has shown that major depression is characterized by disrupted inflammatory pathways, including cytokine expression, such as interleukin-1b (IL-1b), IL-6, interferon g (IFN-g) and tumor necrosis factor-a (TNF-a) or IL-17." (PMID 35407663, 2022). "In addition, genetic polymorphisms in inflammatory factors (e.g. IL-1β, TNF, and CRP) are strongly associated with depression and treatment outcomes." (PMID 36186850, 2022). "Elevated IL-1β, IL-6 and lowered IL-10 in the model rats indicated there may be a low Th2 or/and M2 immune response in pain and depression comorbidities." (PMID 35733107, 2022). "Additionally, multivariate logistic regression analyses disclosed that TNF‐α (both P < 0.05) and IL‐1β (both P < 0.001) were independently correlated with increased anxiety and depression risks in NSCLC survivors." (PMID 34697903, 2022). "It was reported that mean levels of IL-1β, IL-4, IL-8 increase as depression became more severe." (PMID 35326343, 2022). "Interestingly, BDNF emerged among the genes shared by depression and atherothrombosis, and it was well-connected to all the genes identified in both databases, namely, IL-1β, IL-6, IL-18, TNF, APOE, ACE, MTR, MTHFR genes." (PMID 35911513, 2022). "Clinical and animal studies of an epilepsy model, where anti-inflammatory drugs such as celecoxib (cyclooxygenase inhibitor), Anakinra (IL-1β antagonist), and minocycline (microglial inhibitor) ameliorated depression, also support this hypothesis." (PMID 35504954, 2022). "Noteworthy, inflammatory processes are involved in the pathophysiology of depression and microglia dysfunction is considered a key event in depression, with patients showing increased blood concentration of proinflammatory cytokines such as IL-1β, IL-6 and TNF-α." (PMID 36232813, 2022). "On the other hand, it has been suggested that increasing of pro-inflammatory cytokines including IL-1β, IL-6 and hs-CRP elevates function of mitochondria and reactive oxygen species (ROS) that by affecting function of neurons could cause depression." (PMID 36368945, 2022). "High IL-1β (P=0.011, adjusted P=0.044), IL-6 (P=0.010, adjusted P=0.040), and IL-17 (P=0.011, P=0.044 after adjustment), but not TNF-α (P=0.104, P=0.416 after adjustment), were associated with depression occurrence." (PMID 35239774, 2022).
depression (continued). "The activation of the inflammatory response system during stress exposure is associated with hypothalamic–pituitary–adrenal axis (HPA) hyperactivity, indicating that HPA hyperactivity in depression is contributed by proinflammatory cytokines, such as IL-1β and TNFα." (PMID 35328018, 2022). "Untreated patients suffering from depression have been found to have elevated IL-1β levels in CSF." (PMID 36614020, 2022). "It has been found recently that IL-1β and IL-18 play an important role in depression." (PMID 35069768, 2022). "Our results provide new insights into some of the bases for EGCG action in depression, which we hypothesize may involve modulation of IL-1β peripheral blood levels, BDNF expression in the hippocampus and neuronal ultrastructural damage in CUMS disorder." (PMID 35939172, 2022). "We analyzed plasma IL-1β, IL-2, -6, -8, -10, TNF, kynurenine, tryptophan, serotonin, kynurenic- quinolinic- and picolinic acids and used mixed-effects models to assess the association between biomarkers and depression severity." (PMID 35078975, 2022). "The concentration of IL-1β increased with the severity of depression and when concurrent with PTSD." (PMID 35326343, 2022). "This raises the question of whether this occurrence is more related to depression or acute reaction to stress, as mice under stress expressed more IL-1β than controls." (PMID 36614020, 2022). "This suggests that the increase in the protein expression of NLRP3, caspase-1, and IL-1β may have participated in anxiety-like and depression-like behavioral phenotypes in mice with atopic dermatitis." (PMID 36267291, 2022). "Similarly, a single case study report of new-onset depression following initiation of anti-IL1β (anakinra) in a patient with rheumatoid arthritis was reported in 2011." (PMID 34648616, 2022). "Moreover, the cytokines that appeared increased in plasma after ISO, TNFα, IL6, and IL1β, are also the ones shared between depression and heart failure." (PMID 35936761, 2022). "One important cytokine involved in depression, which is upregulated in RA, is IL1β." (PMID 36422176, 2022). "In addition, IL-1β level was also increased significantly in mice with memory impairment and depression after peripheral nerve injury." (PMID 34813418, 2022). "Furthermore, clinical researches showed that patients with depression had elevated IL-1β, IL-6, and TNF-α levels." (PMID 36578534, 2022). "Therefore, after adjusting covariates by multivariate logistic regression analyses, only TNF‐α and IL‐1β were independently correlated with increased anxiety and depression risks in NSCLC survivors." (PMID 34697903, 2022). "Depression severity and concentrations of the biomarker IL-1β may thus be interlinked amongst people living with HIV." (PMID 35618889, 2022). "A positive correlation between serum IL-1β and the severity of depression also was observed." (PMID 36142317, 2022). "In addition, AC-induced behavioural changes correlate with increased serum IL-6 levels and brain IL-1β mRNA, with these data being analogous to those reported previously in animal models of depression-like behaviour and in MDD." (PMID 34888704, 2022). "Furthermore, they induced TNF-α, IL-1β, and IL-6 expression NF-κB+/Iba1+ cell population in the hippocampus and corticosterone and IL-6 levels in the blood, resulting in anxiety/depression through the regulation of neuroinflammation." (PMID 33731795, 2021). "The possible mechanism is that IL-1β activates IL-1 receptor type I in hippocampal neural stem cells, which affect nuclear factor kappaB signal transduction pathway, reduce the proliferation of hippocampal cells, and then lead to depression." (PMID 34479552, 2021). "The correlation between IL-1β levels in the mothers and their depressed/anxious children may indicate familial vulnerability to depression and anxiety." (PMID 34083584, 2021).
depression (continued). "To test the effect of TSD+LT on peripheral inflammatory markers associates with treatment resistant depression, in a proof-of-concept study here we studied Interleukin-1β (IL-1β), which has been consistently associated with non-response to drugs." (PMID 34539454, 2021). "Serum IL1β levels strongly correlated with depression severity in late-life depression." (PMID 35002816, 2021). "Clinical studies have indicated that patients suffering from depression showed significantly higher levels of proinflammatory cytokines, including interleukin-1β (IL-1β), interleukin-6 (IL-6), tumor necrosis factor alpha (TNF-α), C-reactive protein (CRP), and inflammasome, than healthy people." (PMID 33466877, 2021). "So, increased TNF-α and IL-1β in the hippocampus in our work may contribute to depression-like behaviors by affecting adult hippocampal neurogenesis." (PMID 34827513, 2021). "A significant increase in the secretion of IL-1β has been demonstrated in patients with depression." (PMID 33920992, 2021). "The inflammasome hypothesis of depression states that psychological stress activates NLRP3 and proposes the pathway between NLRP3 to IL1β as an underlying mechanism of MDD." (PMID 35002816, 2021). "However, oral administration of buspirone significantly reduced IS-induced anxiety-/depression-like behaviors and suppressed IL-1β and TNF-α expression and NF-κB+/Iba1+ cell population in the hippocampus." (PMID 33731795, 2021). "In people with MS and comorbid fatigue and/or depression there is reported increased serum and cerebrospinal fluid concentration of inflammatory mediators such as tumor necrosis factor, interleukins (IL-1a, IL-1b, IL-6), interferon γ and neopterin." (PMID 35242093, 2021). "Furthermore, fecal microbiota transplantations suppressed IS-induced TNF-α, IL-1β, and IL-6 expression and NF-κB+/Iba1+ cell population in the hippocampus, resulting in the amelioration of anxiety/depression." (PMID 33731795, 2021). "In addition, IL-1β in the brain is a key mediator of depression-like behavior induced by acute and chronic stress." (PMID 34930362, 2021). "Besides, it also reduced the expression of TNF-α and IL-1β in the hippocampus and serum of depression mice, and inhibited the M1-like activation of microglia." (PMID 34497527, 2021). "The expression levels of TNF-α (p < 0.01), IL-6 (p < 0.05), and IL-1β (p < 0.01) in the CUMS group were significantly higher than those in the control group, which indicated that the occurrence of depression was associated with the production of inflammatory factors." (PMID 35185541, 2021). "Thus, downregulation of P2Y12 in the mPFC decreased the expression of IL-1β and alleviated the comorbidity of visceral pain and depression in IBD mice." (PMID 34930362, 2021). "TNF-α and IL-1β are also increased in major depressive, anxiety and other psychiatric disorders." (PMID 34206415, 2021). "As well as IL-6, IL-1β is one factor with notable implication in the pathophysiology of depression." (PMID 34358084, 2021). "Furthermore, tumor necrosis factor-α (TNF- α), interleukin-1β (IL-1β), and interleukin-6 (IL-6) measured in the cerebrospinal fluid of MS patients correlate with depression scores." (PMID 34764926, 2021). "Chronically activated microglia, increased cell density and hyper-ramified morphology, and the enhanced release of pro-inflammatory cytokines, e.g., TNF-α, IL-1β, and IL-18, are observed in response to stress, major depression, or AD, leading to disease progression and brain damage." (PMID 34109176, 2021). "It is worth exploring whether the P2Y12/IL-1β pathway in microglia of the mPFC contributes to the comorbidity of visceral pain and depression in IBD." (PMID 34930362, 2021). "Moreover, suicide victims with depression showed higher levels of IL-1β, IL-6 and TNF in postmortem brains, while the receptors for the production of these cytokines, such as Toll-like receptor 3 (TLR3) and TLR4, were also affected." (PMID 34827513, 2021).
depression (continued). "IL-1β was found to be present in abnormally high levels in plasma, CSF, and postmortem brain tissue of individuals with mood disorders and its levels correlated positively with the severity of depression." (PMID 34200240, 2021). "Although there were no consistent results in pediatric depression, IL-1β levels were significantly associated with pediatric depression, and higher in MDD patients than in HCs." (PMID 34576215, 2021). "Microglial is activated in neuroinflammation with an ameboid feature, which is characterized by enlarged cell bodies and synaptic retraction, contributing to the development of depression and produce pro/anti-inflammatory cytokines such as IL-1β, TNF-α, and IL-650,51." (PMID 34103482, 2021). "Furthermore, central and peripheral pro-inflammatory cytokines; tumor necrosis factor-alpha (TNF-α), interleukin-6 (IL-6), and interleukin 1β (IL-1β) were reported to have a strong correlation with depression." (PMID 34804417, 2021). "Exposure to stressors including immobilization, antibiotics, or pathogen infection causes anxiety-like behaviors in rodents and induced the expression of proinflammatory cytokines TNF-α, IL-1β, and IL-6 in the hippocampus and colon, resulting in the occurrence of anxiety/depression and colitis." (PMID 33731795, 2021). "Furthermore, previous studies have revealed that functional allelic variants of the IL-1β and TNF-α genes increase the risk of depression and are associated with decreased responsiveness to antidepressant therapy." (PMID 34490521, 2021). "Furthermore, meta-analyses assessing various cytokine levels after anti-depressant treatment in people with depression show significant decreases in IL-6, IL-1β, and CRP." (PMID 39296317, 2021). "Besides, MS increased depression and anxiety behavior with an increased level of IL-1β in the ventral hippocampus (vHIP), prefrontal cortex (PFC) and serum, a decreased level of IL-10 in HPV." (PMID 34890365, 2021). "The anti-inflammatory effect of MSC-Exos, especially the inhibition of IL-1β, may have a certain treatment prospect for epileptic comorbidity depression." (PMID 32528321, 2020). "In addition, in our reserpine-induced animal model of depression, levels of IL-1β, IL-6, and TNF-α were significantly higher than those in control mice." (PMID 32754030, 2020). "IL-4 is an important cytokine that helps in higher brain functions, such as memory and learning; IL-1β, which we also found increased during infection, has been suggested to exert a negative effect on cognitive behavior, characterized by sickness, depression, and stress." (PMID 32635653, 2020). "Both IL-6 and IL-1β are important in the pathophysiology of major depression." (PMID 33029297, 2020). "Moreover, we also observed an inverse correlation between IL-1β and satisfaction with life and ratings of ego dissolution, and a positive correlation with depression and 5D-ASC ratings, post-session." (PMID 31822925, 2020). "In addition, we assessed the mRNA expression of Tnf and Il1β in tissue relevant for mechanical allodynia, spontaneous pain, and depression-like behavior." (PMID 32510006, 2020). "Moreover genome-wide association stud (GWAS) analysis showed that various proinflammatory cytokines including IL-1β, TNF, and CRP have been linked to depression and response to treatment." (PMID 32380663, 2020). "IL-1β and IL-6 have been shown to be increased in some brain regions of patients with depression." (PMID 32321532, 2020). "In addition, various studies demonstrated increased serum levels of TNF-α, IL-1β, and IL-6 in patients with depression." (PMID 32184729, 2020). "Given the known action of curcumin on some immunoinflammatory pathways, the pivotal role of IL-1β and microglia activation in the pathophysiology of depression, and the relevance of these processes to the therapeutic properties of curcumin, we can highlight a probable role for the inflammasomes." (PMID 33329109, 2020).